MIR365A (microRNA 365a)
Synonyms: hsa-mir-365-1; MIR365-1; MIRN365-1; hsa-mir-365a; mir-365a
Gene: MicroRNA gene on chromosome 16 (14,309,285 to 14,309,371, forward strand). Ensembl gene ENSG00000199130.
Gene Ontology:
Cellular component: RISC complex
Homologues: Orthologues: chimpanzee ptr-mir-365-1 (100% identical), guinea pig MIR365A (100% identical), dog MIR365A (99% identical), macaque MIR365A (99% identical), mouse Mir365-1 (99% identical), pig MIR365A (99% identical), rat Mir365-1 (99% identical), tropical clawed frog xtr-mir-365-1 (93% identical), zebrafish mir365-1 (90% identical), rabbit MIR365A (69% identical). Paralogues in human: MIR365B (83% identical).